ERCC5 (ERCC excision repair 5, endonuclease)
Diseases named in the same sentence as ERCC5 in open-access papers (continued):
Sharing a sentence is not in itself a finding about the gene and the disease.
diffuse large B-cell lymphoma (1 paper, 2024). "Moreover, in diffuse large B-cell lymphoma (DLBCL), an aggressive form of non-Hodgkin lymphoma, high levels of eIF4B increase the expression of key survival proteins, including BCL-2, DAXX and ERCC5, and are prognostic of poor patient outcome." (PMID 39225047, 2024).
Hereditary breast and ovarian cancer syndrome (1 paper, 2025). An autosomal dominant inherited syndrome caused by mutations in the BRCA1 or BRCA2 genes.
liver disease (1 paper, 2024). "Some studies have suggested that the ERCC5 gene polymorphism can be used as a de novo marker of liver disease." (PMID 40626125, 2024).
liver dysfunction (1 paper, 2024). "In addition to the typical manifestations of XP/CS, the patient with the XP/CS phenotype caused by a novel ERCC5 mutation reported in this article developed severe and progressive liver dysfunction after drug induction." (PMID 40626125, 2024).
Lymphatic Metastasis (1 paper, 2016). Transfer of a neoplasm from its primary site to lymph nodes or to distant parts of the body by way of the lymphatic system. "(AA+AG) genotype of ERCC5 rs2094258 polymorphism could predict better OS in patients subgroups of age>60, Borrmann III–IV, TNM stage III-IV, lymphatic metastasis and diffuse-type." (PMID 27340861, 2016).
lymphoma (1 paper, 2019). A malignant (clonal) proliferation of B- lymphocytes or T- lymphocytes which involves the lymph nodes, bone marrow and/or extranodal sites. "These include AKT3, ERCC5 and maybe ARID1A as general MMR-D targets, but also POLE as lymphoma-specific neoantigen." (PMID 31581674, 2019).
metastatic prostate carcinoma (1 paper, 2024). A carcinoma that arises from the prostate gland and has spread to other anatomic sites.
mucinous adenocarcinoma (1 paper, 2018). An invasive adenocarcinoma composed of malignant glandular cells which contain intracytoplasmic mucin. "Another NER member with significantly increased mRNA expression was ERCC5 in rectal mucinous adenocarcinoma (fold change = 2.121, P = 0.005) according to Kaiser Colon dataset." (PMID 29568775, 2018).
neuroendocrine tumors (1 paper, 2023). "Importantly, MYC‐driven non‐neuroendocrine tumors which are resistant to first‐line therapies show reduced CDKN1A/p21 expression and increased ERCC5/XPG indicating they are primed for response to lurbinectedin–berzosertib combination." (PMID 37491889, 2023).
rectal cancer (1 paper, 2018). A primary or metastatic malignant neoplasm that affects the rectum. "In addition, ERCC5 and ERCC6 showed marginally significant association with recurrence of rectal cancer with a P value of 0.51." (PMID 29568775, 2018).
squamous cell carcinoma of the head and neck (1 paper, 2012). "Furthermore, several studies suggested that variations in ERCC5 transcript and protein levels as well as ERCC5 variant genotypes were associated with risk of squamous cell carcinoma of the head and neck (SCCHN), which shares similar risk factors with ESCC." (PMID 22848513, 2012).
UV-sensitive syndrome (1 paper, 2016). UV-sensitive syndrome is a condition that is characterized by sensitivity to the ultraviolet (UV) rays in sunlight. "Interestingly, our results also found ERCC2(XPD), ERCC3(XPB) or ERCC5(XPG) mutations in two cases of UV-sensitive syndrome and in two cases with mixed XP/CS phenotypes." (PMID 27004399, 2016).
xeroderma pigmentosum group (1 paper, 2012). "The excision repair cross complementing group 5 (ERCC5) gene, also known as the xeroderma pigmentosum group G (XPG) gene, is a member of the flap structure-specific endonuclease 1 (FEN1) family and encodes a protein of 1186 amino acids." (PMID 22815677, 2012).
cancer (69 papers, 2011 to 2026). A tumor composed of atypical neoplastic, often pleomorphic cells that invade other tissues. "In particular, it has been found that polymorphisms in the ERCC5 gene are associated with cancer risk." (PMID 37189432, 2023). "The purpose of the current study was to elucidate the role of all studied SNPs in ERCC4 and ERCC5 in the tendency of all implicated types of cancer." (PMID 36033436, 2022). "ERCC4 and ERCC5 were indispensable component members of the NER pathway; numerous studies were conducted to investigate the correlations between the SNPs of ERCC4 or ERCC5 and the risk of cancers." (PMID 36033436, 2022). "The heterozygous and homozygous variant types of ERCC5 rs17655 were associated with patients who had a positive family history of cancer (OR = 2.1, 95% CI = 0.9–5.04; P = 0.05)." (PMID 36686735, 2022). "Meta-analyses aiming to explore the relationship between ERCC4 and ERCC5 variants and the kinds of human cancers were continuously published." (PMID 36033436, 2022). "ERCC5 single nucleotide polymorphisms are capable of affecting DNA repair capacity and thus interfering with cancer susceptibility." (PMID 35934844, 2022). "With the exception of rs17655 (C vs. G), six SNPs (rs1047768, rs2094258, rs2296147, rs2228959, rs751402, and rs873601) of ERCC5 were also demonstrated to significantly alter the susceptibility of cancers." (PMID 36033436, 2022). "Summary of functional annotations for four single-nucleotide polymorphisms in ERCC4 and ERCC5 with five cancer sites risk (strong epidemiological credibility)." (PMID 36033436, 2022). "Of note, HPV-negative HNSCC with NSD1 mutations were associated with a decreased expression of ERCC5 mRNA levels, and inactivation of ERCC5 has been previously shown to increase sensitivity to cisplatin in a variety of cancers." (PMID 36230787, 2022). "In summary, mutations or low expression in ERCC5 is associated with poor prognosis in some types of cancer, consistent with a need to balance XPG levels for its multiple functions in genome stability." (PMID 34966786, 2021). "More importantly, in the only meta-analysis performed to date, a decrease in cancer risk in ERCC5 rs2227869 heterozygotes (and for the C allele) has also been reported." (PMID 31374908, 2019). "In fact, only a few studies have considered the putative contribution of ERCC5 rs2227869 to cancer susceptibility, most being inconclusive." (PMID 31374908, 2019). "Our meta-analysis examined the influence of the ERCC5 rs1047768 and rs17655 polymorphisms on the sensitivity to platinum-based chemotherapy in cancers." (PMID 29416691, 2018). "Overall, 12 studies involving 1,506 cancer patients were eligible for the meta-analysis for the ERCC5 rs1047768 polymorphism." (PMID 29416691, 2018). "Meta-analysis of the association between the ERCC5 Asp1104His polymorphism and cancer risk under the XP recessive genetic model for 49 studies." (PMID 22815677, 2012). "To derive a more precise estimation of the association between the ERCC5 Asp1104His polymorphism and overall cancer risk, we performed a meta-analysis of 44 published case-control studies, in which a total of 23,490 cases and 27,168 controls were included." (PMID 22815677, 2012). "It has been observed that rare mutations in ERCC5 are causative of DNA repair deficient diseases characteristic of abnormal apoptosis and a high level of cancer risk." (PMID 22848513, 2012). "Studies have found an association between ERCC5 genetic variations and different cancers." (PMID 36686735, 2022). "Furthermore, a comprehensive research synopsis with systematic functional annotation has not been performed to evaluate the epidemiological evidence of genetic associations between ERCC4 or ERCC5 genes and the risk of cancers till now." (PMID 36033436, 2022).
cancer (continued). "Single nucleotide polymorphisms in ERCC5 may change its activity or expression, affecting DNA repair function, resulting in the alteration of cancer treatment effects, as treatment outcomes depend on the genetic variant of the gene present." (PMID 36686735, 2022). "In this updated meta-analysis concerned with ERCC4 and ERCC5 single-nucleotide polymorphisms (SNPs), 160 eligible publications were identified, and we exerted the meta-analysis of correlations between 24 variants and 19 types of cancer." (PMID 36033436, 2022). "The current results suggest that variations in ERCC5 may contribute to BC development and that their genetic anomalies may be associated with cancer risk and may be used as a biomarker of clinical outcome." (PMID 36686735, 2022). "Indeed, previous studies have linked ERCC5 SNVs to soft tissues cancer susceptibility, including endometrial and thyroid." (PMID 33821390, 2021). "In addition, genetic studies identified an association between late radiation-induced fibrosis and polymorphisms in the ATM, TGFB, ERCC1, and ERCC5 genes for cancer patients who had been treated with radiotherapy." (PMID 32775415, 2020). "The rs17655 polymorphism, leading to the replacement of aspartate with histidine at codon 1104 in ERCC5 protein, may cause an alteration in the protein function, thereby likely affecting DNA repair ability, genome integrity, and cancer predisposition." (PMID 29779017, 2018). "This meta-analysis suggests that it is unlikely that the ERCC5 Asp1104His polymorphism may contribute to individual susceptibility to cancer risk." (PMID 22815677, 2012). "Numerous studies have reported that altered ERCC5 transcript expression modulate transcription domain-associated repair capacity and other important phenotypic effects, including inter-individual variation in the incidence of several cancer types." (PMID 22848513, 2012). "Therefore, we performed a meta-analysis to identify statistical evidence for an association between the ERCC5 Asp1104His polymorphism and cancer risk using all published data to date." (PMID 22815677, 2012). "A growing number of genetic evidence indicated that the single-nucleotide polymorphisms (SNPs) in the ERCC4 and ERCC5 genes may vary susceptibility to malignant tumor; previous studies have demonstrated that ERCC4 rs1800067 was associated with the risks of lung cancer, breast cancer, and glioma." (PMID 36033436, 2022). "It is biologically plausible that the Asp1104His polymorphism, causing a change from aspartate to histidine at codon 1104 in ERCC5 protein, may result in an alteration of the gene function, thus likely altering risk of developing cancers, possibly following a recessive genetic model." (PMID 22815677, 2012). "Excision repair cross complementing group 5 (ERCC5 or XPG) plays an important role in regulating DNA excision repair; its functional single nucleotide polymorphisms (SNPs) may alter DNA repair capacity and thus contribute to cancer risk." (PMID 22848513, 2012). "Moreover, excision repair cross‐complementing (ERCC) genes and key components of the nucleotide excision repair pathway are regarded as crucial factors for DNA repair capacity, and ERCC5 regulates DNA excision repair, which may contribute to liver function and even cancer risk." (PMID 40626125, 2024). "Hence, mutations in ERCC5 might enhance platinum effect on cancer cells." (PMID 35852645, 2022). "In this extensively updated meta-analysis, 11 SNPs were proven to be significantly associated with cancer risk, and four variant-related cancer risks (one for ERCC4 and three for ERCC5) were graded as strong-credibility cumulative epidemiological evidence." (PMID 36033436, 2022). "A small, but unique group of 16 non-FAP mesenteric desmoid was found to harbor genetic alterations in cancer associated genes other than APC, including CHEK2, BLM, ERCC5, MSH6, and PALB2." (PMID 34359575, 2021).
cancer (continued). "A total of 13 SNPs in ERCC5, ERCC2, ERCC1, XPC, and XPA genes, which have been found to affect the risk and/or survival of cancers, were selected in the present study." (PMID 30609649, 2019). "Inactivation of ERCC5 has been shown to result in increased sensitivity to cisplatin in a variety of cancers." (PMID 31321084, 2019). "While J21 cells are a sub-clone of a cancer cell line (HT1080) with known defects in DNA repair genes (e.g. ERCC5, FANCC, MSH3, and WRN), hTERTs are an immortalized, non-cancerous cell line that does not contain any known defects." (PMID 25893404, 2015). "The biological mechanisms of the ERCC5 gene in carcinogenesis may be complicated, among which nsSNPs, leading to an amino acid change in the protein product and modulating the individual DNA repair capacity phenotype, may account for some of the known genetic variations related to risk of cancers." (PMID 22815677, 2012). "We found that the LD among these three SNPs of ERCC5 was incomplete in all control subjects (rs2094258 and rs2296147: r2 = 0.163; rs2094258 and rs873601: r2 = 0.438; rs873601 and rs2296147: r2 = 0.102), suggesting that variant haplotypes may play a role in cancer risk." (PMID 22848513, 2012). "We checked the significant germline mutations, the mutations which could cause effects on cancer development or progression, only very three gene mutations were detected, including RUNX1, CDKN2A, and ERCC5." (PMID 39105897, 2024). "A total of 12 SNPs of the ERCC5 gene and 15 types of cancer were involved into meta-analyses." (PMID 36033436, 2022). "Although the detailed mechanism by which the SNPs in ERCC5 are associated with CRC susceptibility is unclear, our findings could provide new insights into the genetic factors underlying cancer susceptibility and carcinogenesis." (PMID 36386844, 2022). "Other mutated cancer genes included those involved in Wnt signaling (APC, AMER1), mitogen signaling (KRAS, BRAF), epigenetic modification (ARID1A, ARID2, DNMT3A, NCOA3) and DNA repair (RAD50, BRIP1, ERCC5, RECQL4)." (PMID 33776923, 2021). "On the basis of these study results, we speculate that the CC genotypes of ERCC5 rs17655 and ERCC1 rs735482 may increase the DNA-repair capacity of cancer cells, leading to increased susceptibility to recurrence." (PMID 30609649, 2019). "ERCC5 is a well-known gene which has great impact on cancer." (PMID 28924235, 2017). "In summary, our meta-analysis shows that the ERCC5 Asp1104His polymorphism appeared to be unlikely to confer susceptibility to cancers." (PMID 22815677, 2012). "These suggest a possible link between the ERCC5 function and development of cancer." (PMID 22815677, 2012). "For the patients with single primary cancer, among 542 evaluable patients (those with both germline and somatic mutations which were in same or different genes), 25 patients (4.6%) had biallelic events, and the involved genes included ATM, BRCA1, BRCA2, BRIP1, and ERCC5." (PMID 37885353, 2024). "Enzyme repair complementary complex 5 (ERCC5) is one of the key players for repairing platinum DNA adduct through the dual incision at both the 5’ and 3’ sides of the adduct which may lead to a decrease in platinum activity against cancer." (PMID 35852645, 2022). "We therefore tested whether ERCC5 (XPG) alterations in terms of simple coding mutations (single base substitutions and small indels) or changes in gene expression in tumors represent a risk factor in cancer." (PMID 34966786, 2021). "A total of 19 types of cancer and 24 SNPs of both ERCC4 and ERCC5 were incorporated into meta-analysis because there were at least two serviceable datasets." (PMID 36033436, 2022). "In family F1506, the index carrier harbouring ERCC5 c.2556 A>G also had a remarkable family history of diverse cancer types, whereas the index carrier of NEIL1 c.248G>T; c.1268-1G>T from family F1601 had a cancer family history consistent with HBOC syndrome." (PMID 36969007, 2023).
cancer (continued). "Emerging evidence associates the expression levels of genes involved in the NER process and some types of cancer, while data on STS are limited, so we evaluated the gene expression of three key genes (ERCC1, ERCC2 and ERCC5) in the NER pathway in 24 tissue samples from the 32 patients in our cohort." (PMID 35955506, 2022). "Of the coexpressed genes, NAXD and BIVM also displayed hazard ratios comparable to that of ERCC5 in LGG, although their association with cancer has not been reported." (PMID 34966786, 2021). "There were some reports on the prognosis of ERCC5 mRNA expression in malignant tumors, but none in GC." (PMID 30417012, 2018). "Therefore, whether or not an association between ERCC5 SNPs with cancer risk is cancer-specific needs to be validated in additional large studies of different cancer types, either in additional groups of homogenous ethnicity or in more ethnically diverse groups." (PMID 22848513, 2012). "As the ERCC5 (XPG) correlations could point to multiple associations, we tested other NER proteins, e.g., XPA and XPC, and found that they generally did not exhibit the same characteristics in these three cancer types, except for XPA in MESO." (PMID 34966786, 2021).